Y_RNA (Y RNA )
Gene: Miscellaneous RNA gene on chromosome 6 (16,232,231 to 16,232,330, reverse strand). Ensembl gene ENSG00000207193.
Homologues: Orthologues: chimpanzee Y_RNA (99% identical). Paralogues in human: RNY3 (86% identical), Y_RNA (86% identical), Y_RNA (85% identical), Y_RNA (84% identical), RNY3P1 (83% identical), Y_RNA (83% identical), RNY3P4 (82% identical), Y_RNA (82% identical), RNY3P9 (81% identical), Y_RNA (81% identical), RNY3P14 (80% identical), RNY3P16 (80% identical), and 93 more.